AKR1C2 (aldo-keto reductase family 1 member C2)
Description:
Cytosolic aldo-keto reductase that catalyzes NADPH-dependent reduction of ketosteroids to hydroxysteroids. Displays broad substrate specificity with distinct positional and stereochemistry, primarily generating 3alpha-hydroxysteroids, but also 3beta-, 17beta- and 20alpha-hydroxysteroids. Required for male sex determination as a component of the 'backdoor' androgen biosynthesis pathway that generates 5alpha-dihydrotestosterone (5alpha-DHT) via pregnanes. Acts together with AKR1C4 to convert 5alpha-dihydroprogesterone (5alpha-DHP) to 3alpha-hydroxy-5alpha-pregnan-20-one (3alpha,5alpha-THP/allopregnanolone), leading to 5alpha-DHT secretion necessary for embryonic gonad differentiation into testis. In androgen catabolism, may predominantly act as a phase I enzyme by introducing a hydroxyl group prior to conjugation. It can nevertheless participate in the alternative phase II pathway by directly reducing sulfate- or glucuronide-conjugated androgens. In neurosteroid biosynthesis, may preferentially reduce 5alpha-dihydroprogesterone (5-alpha-DHP) and 5alpha-dihydrodeoxycorticosterone (5-alpha-DHDOC) precursors to 3alpha-hydroxy-5alpha-pregnan-20-one (3alpha,5alpha-THP/allopregnanolone) and 3alpha,21-dihydroxy-5alpha-pregnane-20-one (3alpha,5alpha-THDOC) neuroactive steroids known to alter neural excitability via allosteric activation of gamma-aminobutyric acid type A receptors (GABAAR). Regulates ligand availability for steroid hormone receptors. Catalyzes the inactivation of 5alpha-DHT and progesterone converting them into 3alpha/beta-androstanediols and (20S)-hydroxypregn-4-en-3-one, respectively. Can form 17beta-hydroxysteroids such as testosterone and estradiol albeit with lower efficiency when compared to AKR1C3. May contribute to the metabolism of adrenal-derived androgens via reduction of 11-keto-5alpha-androstane-3,17-dione (11K-Adione) into 11-ketoandrosterone (11KAST) and of 11-ketodihydrotestosterone (11KDHT) into 11-keto-5alpha-androstane-3alpha/beta,17beta-diol (11K-A3alphadiol). May also play a role in prostaglandin (PG) metabolism by reducing PGD2 to 11beta-PGF2. Also able to metabolize xenobiotics (S)- indan-1-ol and trans-1,2-dihydrobenzene-1,2-diols. In vitro can efficiently catalyze bidirectional conversion between ketosteroids and hydroxysteroids using NADPH/NADP(+) or NADH/NAD(+) as cofactors. In vivo however, the reductase activity prevails since the major reducing cofactor NADPH inhibits NAD(+)- dependent oxidase activity.
Synonyms: DD-2; DD2; DD/BABP; DDH2; DD; BABP; HAKRD; MCDR2; AKR1C-pseudo; HBAB; SRXY8; TDD
Tractability: Small molecule: a structure with a bound ligand is known; a high-quality ligand is known; it has a high-quality binding pocket; it belongs to a druggable protein family. PROTAC: ubiquitination databases record sites on it; its protein half-life has been measured; a small molecule that binds it is known.
Target class: Enzyme; Oxidoreductase
Gene: Protein-coding gene on chromosome 10 (4,987,775 to 5,018,031, reverse strand). Ensembl gene ENSG00000151632.
Subcellular location: Cytoplasm, cytosol
Subcellular location (Human Protein Atlas): Cytosol; Nucleoplasm; Endoplasmic reticulum; Nucleoli fibrillar center
Pathways (Reactome):
Metabolism: Synthesis of bile acids and bile salts via 24-hydroxycholesterol; Synthesis of bile acids and bile salts via 27-hydroxycholesterol; Synthesis of bile acids and bile salts via 7alpha-hydroxycholesterol
Gene Ontology:
Molecular function: 3-alpha-hydroxysteroid 3-dehydrogenase [NAD(P)+] activity; aldose reductase (NADPH) activity; androsterone dehydrogenase [NAD(P)+] activity; bile acid binding; carboxylic acid binding; estradiol 17-beta-dehydrogenase [NAD(P)+] activity; ketosteroid monooxygenase activity; oxidoreductase activity, acting on NAD(P)H, quinone or similar compound as acceptor; prostaglandin D2 11-ketoreductase activity; testosterone dehydrogenase (NADP+) activity; trans-1,2-dihydrobenzene-1,2-diol dehydrogenase activity; 17-beta-hydroxysteroid dehydrogenase (NAD+) activity; 3-beta-hydroxysteroid 3-dehydrogenase (NADP+) activity; alcohol dehydrogenase (NAD+) activity; alcohol dehydrogenase (NADP+) activity; androstan-3-alpha,17-beta-diol dehydrogenase (NAD+) activity; carbonyl reductase (NADPH) activity; indanol dehydrogenase activity; oxidoreductase activity
Biological process: cellular response to jasmonic acid stimulus; cellular response to prostaglandin D stimulus; daunorubicin metabolic process; digestion; doxorubicin metabolic process; epithelial cell differentiation; G protein-coupled receptor signaling pathway; positive regulation of cell population proliferation; positive regulation of phosphatidylinositol 3-kinase/protein kinase B signal transduction; progesterone metabolic process; prostaglandin metabolic process; steroid metabolic process; hormone metabolic process; monocarboxylic acid metabolic process
Cellular component: cytosol
Genetic constraint (gnomAD): Loss-of-function variants: 24 observed, 32.61 expected, observed/expected ratio (o/e) 0.74, 90% interval 0.53 to 1.03. The upper end of that interval is the gene's LOEUF score, 1.03, which puts it in group 4 of 6, group 1 being the genes least tolerant of losing a copy. Missense variants: 253 observed, 297.07 expected, observed/expected ratio (o/e) 0.85, 90% interval 0.77 to 0.94. Synonymous variants: 102 observed, 113.35 expected, observed/expected ratio (o/e) 0.9, 90% interval 0.77 to 1.06.
Homologues: Orthologues: chimpanzee AKR1C2 (88% identical), zebrafish akr1a1a (42% identical), Drosophila melanogaster CG6083 (40% identical), Caenorhabditis elegans Y39G8B.1 (40% identical), zebrafish zgc:56622 (39% identical), Caenorhabditis elegans C07D8.6 (37% identical), Caenorhabditis elegans Y39G8B.2 (33% identical), zebrafish zgc:110366 (32% identical), tropical clawed frog XB5994047 (31% identical), Caenorhabditis elegans F53F1.2 (31% identical), Caenorhabditis elegans F53F1.3 (31% identical), Caenorhabditis elegans C01G5.5 (30% identical), and 9 more. Paralogues in human: AKR1C1 (98% identical), AKR1C3 (87% identical), AKR1C4 (81% identical), AKR1C8 (68% identical), AKR1D1 (58% identical), AKR1B1 (48% identical), AKR1B10 (48% identical), AKR1B15 (46% identical), AKR1E2 (43% identical), AKR1A1 (43% identical), AKR7A2 (27% identical), KCNAB3 (27% identical), and 4 more.
Diseases named in the same sentence as AKR1C2 in open-access papers:
AKR1C2 is named in the same sentence as 64 diseases in open-access papers, as found by Europe PMC text mining. Sharing a sentence is not in itself a finding about the gene and the disease. The quoted sentences say what the papers report.
prostate carcinoma (11 papers, 2010 to 2023). A carcinoma that arises from epithelial cells of the prostate gland. "These AKR1C family members are also involved in steroid metabolism, and selective loss of AKR1C2 in prostate cancer, for example, have been found to promote clonal expansion of tumor cells by enhancement of androgen-dependent cellular proliferation." (PMID 23437342, 2013). "DHT is a key molecule in prostate cancer development and alterations in the expression of AKR1C2 have been linked to benign prostatic hyperplasia and prostate cancer." (PMID 21217827, 2010). "AKR1C1 has a role in controlling plasma progesterone levels in pregnancy while AKR1C2 has been linked to prostate cancer." (PMID 21217827, 2010). "MGST1 was linked with the invasion and chemoresistance in EOC.The loss of AKR1C2 was responsible for the advancement of prostate cancer, but the inactivation of this gene may be associated with the development of EOC." (PMID 30970615, 2019). "AKR1C2, as a risky gene, is correlated with the biochemical recurrence in prostate cancer patients after radical prostatectomy." (PMID 36701414, 2023). "For instance, Wang et al14 and Huang et al22 reported that AKR1C2 functioned as an oncogene in human prostate cancer whereas Ji et al11 obtained opposing results, supporting that AKR1C2 acted as a tumour suppressor gene in human prostate cancer." (PMID 32678482, 2020). "This obvious growth constraint and cell cycle arrest induced in prostate cancer by adiols caused us to confirm the functional expression of the enzymes they originate from, especially AKR1C1 and AKR1C2." (PMID 29682196, 2018). "Meantime, AKR1C2 expression could be elevated by curcumin therapy to give play to the antitumor effects on prostate cancer." (PMID 36701414, 2023). "Furthermore, in PC3 cells, overexpression of AKR1C2 induced PGF2α level and AKR1C2 expression is positively correlated with an increase in the Gleason score, and thus in disease progression in human prostatic cancer." (PMID 32932589, 2020). "The expression of aldo-keto reductase (AKR) family genes, including those for AKR1C1 and AKR1C2, which contribute to the detoxification of lipid peroxidation products, was recently shown to be markedly increased in an established erastin-resistant clone of DU-145 human prostate cancer cells." (PMID 30333913, 2018). "In addition, it is known that the androgen biosynthesis enzymes AKR1C1, AKR1C2, and AKR1C3 are upregulated in prostate cancer." (PMID 29682196, 2018). "The vitamin K-2/SXR mechanism was proven to activate expression of AKR1C1 and AKR1C2 in osteoblastic cells, but TERE1/K-2-mediated activation of SXR has not been previously studied in prostate cancer." (PMID 23919967, 2013).
breast carcinoma (10 papers, 2014 to 2024). "AKR1C1 and AKR1C2 were prognostic factors of breast cancer, and selective loss of these genes may help enhance endocrine therapy in breast cancer." (PMID 34778244, 2021). "AKR1C2 expression is positively correlated with favorable tumor characteristics and prolongs survival time in primary breast cancer patients." (PMID 36835286, 2023). "A search of publicly available databases showed that the expression of the AKR1C1 and AKR1C2 genes is inversely correlated with the in vitro sensitivity to alpelisib in a large panel of breast cancer cell lines." (PMID 37469415, 2023). "Several known proteins (including HSP90AB1, HSPB1, LDHA, ENO1, PGK1, KRT18, and AKR1C2) and pathways were observed between model breast cancer cell lines related to hormone response, cell metabolism, and cell morphology." (PMID 36937585, 2023). "We found that AKR1C2 was specifically downregulated, and the low expression predicted increased OS in LumB-subtype breast cancer." (PMID 33644115, 2021). "Associations of AKR1C2, AKR7A3, and CBR1 with prognosis of breast carcinoma patients revealed by this study should be further followed in independent validation and functional studies." (PMID 25526449, 2014). "AKR1C2 has an inhibitory effect in the development of squamous cell carcinoma and breast cancer." (PMID 33644115, 2021). "Further studies are required to determine the function of AKR1C2 in LumB-subtype breast cancer." (PMID 33644115, 2021). "In general, the analytical data suggest that STAC2, FREM1, and AKR1C2 may be involved in the tumorigenesis to improve OS of patients with LumB-subtype breast cancer." (PMID 33644115, 2021). "CBM effectively prevented the inhibition of COX-1, COX-2, AKR1C1, and AKR1C2 while retaining AKR1C3 inhibition, making it a valuable molecular probe for studying AKR1C3’s role in breast cancer signaling and proliferation." (PMID 38523637, 2024). "In the context of breast cancer, which involves the use of anti-estrogen agents and aromatase inhibitors in hormone receptor-positive cases, AKR1C1, AKR1C2, and AKR1C3 have been found to be upregulated in tamoxifen-resistant breast cancer cells." (PMID 38523637, 2024). "The results showed the AKR1C1, AKR1C2 and AKR1C3 were highly expressed in TAM-resistant breast cancer cells." (PMID 34886806, 2021). "The function of AKR1C1, AKR1C2 and AKR1C3 genes in TAM-resistant breast cancer cells was revealed by bioinformatics analysis and further confirmed by biological experiments." (PMID 34886806, 2021). "In the selected key specific DEGs for LumB-subtype breast cancer, the expression of CNTD2, NEURL, STAC2, AKR1C2, IL6, FREM1, and HOXA4 were significantly correlated with the prognostic survival of the patients." (PMID 33644115, 2021). "The protein expression levels of AKR1C1, AKR1C2 and AKR1C3 in TAM-sensitive and resistant breast cancer cells were compared." (PMID 34886806, 2021). "Therefore, AKR1C2 may play an important role in LumB-subtype breast cancer." (PMID 33644115, 2021). "Compared with TAM-sensitive counterparts, the expression levels of AKR1C1, AKR1C2, and AKR1C3 were up-regulated in TAM-resistant breast cancer cells." (PMID 34886806, 2021). "We found that compared with TAM-sensitive breast cancer cells, the expression levels of AKR1C1, AKR1C2 and AKR1C3 genes were significantly increased in TAM-resistant breast cancer cells." (PMID 34886806, 2021). "Mechanisms of action of AKR1C2, AKR7A3, CYP2B6, CYP3A4, and CBR1 should continue to be further followed in breast carcinoma patients and models." (PMID 25526449, 2014). "Moreover, STAC2, AKR1C2, and HOXA4 can be used as the specific prognostic markers for LumB-subtype breast cancer." (PMID 33644115, 2021). "Taken together, the mechanism of action of AKR1C2 in responders to NACT does not seem to be a result of interactions between AKR1C2 and major drugs used in the breast carcinoma treatment regimens." (PMID 25526449, 2014).
gastric cancer (5 papers, 2023 to 2025). A primary or metastatic malignant neoplasm involving the stomach. "pep-AKR1C2 is encoded by gastric cancer (GC)-derived exosomal lncRNA (exo-lncAKR1C2)." (PMID 41291707, 2025). "lncAKR1C2 is an exosomal lncRNA secreted from gastric cancer cells, and it encodes a micropeptide pep-AKR1C2, which is produced in lymphatic endothelial cells and promotes lymph node metastasis by gastric cancer cells by modulating YAP phosphorylation and increased fatty acid β-oxidation." (PMID 38203767, 2024). "Similarly, pep-AKR1C2, a micropeptide (163 aa) encoded by the exosomal lncRNA lncAKR1C2, has been identified as a key regulator of fatty acid oxidation (FAO) and lymphatic metastasis in gastric cancer (GC)." (PMID 40565374, 2025).
ovarian carcinoma (5 papers, 2022 to 2025). A malignant neoplasm originating from the surface ovarian epithelium. "It was shown that AKR1C2 is upregulated in cisplatin-resistant cell lines of lung, cervical, and ovarian cancers, and its knockdown restores chemosensitivity." (PMID 41009436, 2025). "Inhibition of the AKR1C2 enzyme by ruthenium complexes in chemotherapy-resistant ovarian cancer cell lines has antiproliferative effects." (PMID 40531841, 2025). "The results showed that SNP sites such as AKR1C2 (rs116900756), AKR1D1 (rs9642092), CYP11B1 (rs1134095), CYP3A7 (rs45446698) appeared simultaneously in the MR analysis results of TT and BioT on ovarian cancer, endometrial cancer, endometriosis, PCOS and POF." (PMID 38075074, 2023).
endometrial cancer (4 papers, 2015 to 2024). Primary or metastatic malignant neoplasm involving the endometrium (mucous membrane that lines the endometrial cavity). "Dysregulated AKR1C2 and C3 expression has been linked to the development of prostate, breast and endometrial carcinomas as well as leukemias, likely due to their ability to modify steroid hormones and prostaglandins (PDGs)." (PMID 25769101, 2015). "The human AKR1C2 can interconvert steroidal hormones from their active to inactive forms, thus, representing the potential drug target for the development of reagents in the treatment of hormone‐dependent cancers like prostate, breast and endometrial cancers, as well as in other diseases." (PMID 32678482, 2020).
esophageal squamous cell carcinoma (4 papers, 2016 to 2023). Esophageal squamous cell carcinoma (ESCC) is a type of esophageal carcinoma (EC) that can affect any part of the esophagus, but is usually located in the upper or middle third. "A study also identified that AKR1C2 could be an oncogene in esophageal squamous cell carcinoma through mediating PI3K/AKT pathway." (PMID 36701414, 2023). "Moreover, down-regulated AKR1C2 was found to be correlated with the disease progression in patients with esophageal squamous cell carcinoma." (PMID 36701414, 2023). "Another study identified that the upregulation of AKR1C2 is strongly correlated with the pathological stage and has worse prognosis in patients with esophageal squamous cell carcinoma (ESCC)." (PMID 36701414, 2023).
glioma (4 papers, 2020 to 2023). A benign or malignant brain and spinal cord tumor that arises from glial cells (astrocytes, oligodendrocytes, ependymal cells). "Conversely, only one lost gene, AKR1C2, shared between at least two datasets, was reported as downregulated and associated with high-risk-score glioma in the REMBRANDT data set." (PMID 34827152, 2021). "Since the enzymes responsible for the metabolization of oxcarbazepine (AKR1C1, AKR1C2, AKR1C3, and AKR1C4) are highly expressed in hepatocytes but not in glioma cells, we expect only marginal transformation to MHD in our in vitro proliferation assay." (PMID 37190109, 2023). "Several aldo-keto reductases are responsible for the metabolization of oxcarbazepine (AKR1C1, AKR1C2, AKR1C3, and AKR1C4), which have not been found to be expressed in the brain or in gliomas." (PMID 37190109, 2023).
lung carcinoma (4 papers, 2022 to 2025). "According to certain research, AKR1C2 expression in lung cancer is strongly associated with resistance to cisplatin and adriamycin." (PMID 40531841, 2025). "The expression of AKR1C2 in lung cancer, its correlation with the clinical characteristics of patients, and the biological roles and molecular mechanisms involved were assessed by bioinformatics." (PMID 40531841, 2025). "Our study demonstrates that AKR1C2 knockdown promotes ferroptosis and inhibits malignant biological behaviors in lung cancer cells." (PMID 40531841, 2025). "The effects of AKR1C2 knockdown on the malignant phenotype of lung cancer cells were evaluated using Transwell, wound healing, and CCK8 assays." (PMID 40531841, 2025). "The expression levels of AKR1C2 in normal lung epithelial cells and lung cancer cells were compared by qRT-PCR and Western blot." (PMID 40531841, 2025). "Finally, the impact of silencing AKR1C2 on malondialdehyde, reactive oxygen species, Fe2+ levels, and ferroptosis-related genes in lung cancer cells were experimentally investigated." (PMID 40531841, 2025). "(F) The expression level of AKR1C2 was correlated with the pathological stage of lung cancer." (PMID 40531841, 2025). "Taken together, we suggest that AKR1C2 may promote LUAD by inhibiting ferroptosis, and AKR1C2 knockdown helps to promote ferroptosis in lung cancer cells, thereby inhibiting lung cancer progression." (PMID 40531841, 2025). "(E) The expression level of AKR1C2 was correlated with lymph node metastasis of lung cancer." (PMID 40531841, 2025). "AKR1C2 may be a potential target for the treatment of lung cancer." (PMID 40531841, 2025). "Our analysis also indicated that the three members of the aldo-keto-reductase-1C (AKR1C) family (AKR1C1, AKR1C2, AKR1C3) correlated with resistance to GPX4 inhibitors in lung cancer CLs." (PMID 39995872, 2025). "(C) The expression level of AKR1C2 was not related to the size and infiltration range of lung cancer." (PMID 40531841, 2025). "Likewise, the cisplatin resistance of ovarian, cervical and lung cancers has been reported to be mediated by AKR1C1 and AKR1C2." (PMID 36139836, 2022). "(D) The expression level of AKR1C2 was not related to the distant metastasis of lung cancer." (PMID 40531841, 2025).